PITPNM3 (PITPNM family member 3)
Diseases named in the same sentence as PITPNM3 in open-access papers (continued):
Sharing a sentence is not in itself a finding about the gene and the disease.
tumor (22 papers, 2017 to 2024). "Phosphatidylinositol Transfer Protein, Membrane-Associated 3 (PITPNM3) often bind with chemokine (C-C motif) ligand 18 (CCL18) to promote tumor progression." (PMID 35609322, 2022). "Tregs infiltration is also found in ZNF330 and PITPNM3 single gene immune infiltration analyses, which is a major mechanism of tumour immune escape, and its phenotypic and functional diversity affects its response to therapy." (PMID 39355773, 2024). "CCL18+ TAMs function through signaling pathways involving CCL18 mRNA expression, which promotes tumor metastasis by interacting with receptors like PITPNM3 on tumor cells." (PMID 39457004, 2024). "As a receptor for CCL18, PITPNM3 highly expressed on epithelial and tumor cells in scRNA-seq data and indicated poor prognosis in microarray cohort." (PMID 36850011, 2023). "CCR1 was highly expressed by monocytes and macrophages, CCR5 was highly expressed by T cells and monocytes, while PITPNM3 was highly expressed by epithelial/tumor cells." (PMID 36850011, 2023). "Immunofluorescent, Western Blot, and qPCR showed that C8018‐7840 notably decreased CCL18‐PITPNM3 induced vimentin and recovered CDH1 expression, which further confirmed that C8018‐7840 inhibited PITPNM3 dependent tumor metastasis." (PMID 36285700, 2022). "We measured the expression of CCL18, CCR8 and PITPNM3 in the GMB tumor from patients (16 men and 12 women) using quantitative real-time polymerase chain reaction." (PMID 35955670, 2022). "Expression of PITPNM3 in women was lower in the tumor core relative to both the enhancing tumor region (p = 0.049) and peritumoral area (p = 0.049)." (PMID 35955670, 2022). "Expression of PITPNM3 in the tumor core in the women was also lower than in the men (p = 0.0011), but not statistically significantly (p = 0.062) in the enhancing tumor region in the women." (PMID 35955670, 2022). "Acting as an immunosuppressive cytokine, it causes polarization of macrophages to phenotype M2 and recruits naïve CD4+ T cells into the tumor niche via its receptor PITPNM3, which then differentiate into Treg cells responsible for tumor immune evasion." (PMID 33076281, 2020). "Additionaly, CCL18 is proved to play a crucial role in the migration and EMT processes of tumor cells by activating receptors other than PITPNM3." (PMID 33114763, 2020). "The most important of them in neoplastic diseases is the phosphatidylinositol transfer protein 3 (PITPNM3)/PYK2 N-terminal domain-interacting receptor 1 (Nir1)." (PMID 33114763, 2020). "Our findings further expand our knowledge of extensive PITPNM3 expression and its functional role in the tumor microenvironment, suggesting that CCL18-PITPNM3 could be an attractive therapeutic target in the tumor microenvironment." (PMID 36418470, 2023). "Moreover, PITPNM3 often bind with chemokine (C-C motif) ligand 18 (CCL18) to promote tumor progression." (PMID 35609322, 2022). "For example, in human BC xenografts in humanized mice, blocking the recruitment of naive CD4+ T cells in the tumor by knocking down the expression of PITPNM3, a CCL18 receptor, significantly reduced intragranular regulatory T cells and inhibited tumor progression." (PMID 34257557, 2021). "Therefore, PITPNM3 is a potential target for tumor metastasis." (PMID 36285700, 2022). "In this study we showed that inhibiting naive CD4+ T cell recruitment by knocking down PITPNM3 in tumor-bearing humanized mice could reduce TI Tregs, restore immune killing of tumors and suppress tumor growth and metastases, confirming the role of PITNM3 recognition of CCL18 in TI Treg biogenesis." (PMID 28290464, 2017). "One of the receptors for CCL18 is PITPNM3, which has been extensively studied in the context of CCL18‐dependent migration induction, invasion, and EMT in tumour cells." (PMID 38520216, 2024). "A previous study showed that two CCL18 receptors, PITPNM3 and CCR8, were highly expressed in tumour-infiltrating Tregs." (PMID 37935468, 2024).
tumor (continued). "In the tumor microenvironment, TAMs‐derived CCL18 binds to PITPNM3." (PMID 36285700, 2022). "In addition to PITPNM3, other receptors are also responsible for the CCL18-dependent migration and EMT of tumor cells, for instance CCR8 in bladder cancer cells." (PMID 33114763, 2020). "Thus knocking down PITPNM3 in CD4+ cells reduced TI Tregs and enhanced TI CD8+ T cells, promoting anti-tumor immunity and tumor control." (PMID 28290464, 2017). "While CCL18 has recently been discovered to bind and signal through CCR8, it also signals through a variety of non-traditional receptors, with the most critical in neoplastic disease being phosphatidylinositol transfer protein 3 (PITPNM3)/PYK2 N-terminal domain-interacting receptor 1 (Nir1)." (PMID 38339310, 2024).
retinopathies (1 paper, 2025). "However, overall disease progression and severity were notably attenuated compared to human PITPNM3-associated retinopathy, highlighting limitations in recapitulating the full clinical spectrum within the preclinical setting." (PMID 41148841, 2025). "The involvement of PITPNM3 in numerous retinopathies with high phenotype variation necessitates further investigation." (PMID 41148841, 2025). "In humans, PITPNM3 retinopathies can have decreased visual acuity years before changes are observed on fundus imaging and retinal thickness." (PMID 41148841, 2025). "The study highlights the complex and nuanced nature of PITPNM3-related retinal disorders." (PMID 41148841, 2025).
PITPNM3 also shares sentences with these, for which no sentence is quoted: lung carcinoma (2 papers); non-small cell lung carcinoma (2); oral cancer (2); pancreatic ductal carcinoma (2); glioblastoma (1); head and neck cancer (1); invasive breast carcinoma (1); nasopharyngeal carcinoma (1); ovarian carcinoma (1); ovarian serous cystadenocarcinoma (1); pancreatic adenocarcinoma (1); paraganglioma (1); pheochromocytoma (1); skin cutaneous melanoma (1); thymoma (1); uterine carcinosarcoma (1).